ENSG00000284523 (novel transcript)
Synonyms: LOC105375421
Gene: Long non-coding RNA gene on chromosome 7 (99,252,452 to 99,325,833, reverse strand). Ensembl gene ENSG00000284523.
Gene Ontology:
Biological process: SRP-dependent cotranslational protein targeting to membrane, signal sequence recognition
Cellular component: signal recognition particle, endoplasmic reticulum targeting